MGAT4C (MGAT4 family member C)
Description:
Glycosyltransferase that participates in the transfer of N-acetylglucosamine (GlcNAc) to the core mannose residues of N-linked glycans. Catalyzes the formation of the GlcNAcbeta1-4 branch on the GlcNAcbeta1-2Manalpha1-3 arm of the core structure of N-linked glycans. Essential for the production of tri- and tetra-antennary N-linked sugar chains (By similarity). Does not catalyze the transfer of GlcNAc to the Manalpha1-6 arm to form GlcNAcBeta1-4Manalpha1-6 linkage ('GnT-VI' activity).
Synonyms: hGnT-IV-H; GNTIVH
Tractability: Antibody: UniProt predicts a signal peptide or a membrane-spanning region; the Human Protein Atlas places it where antibodies can reach.
Gene: Protein-coding gene on chromosome 12 (85,955,666 to 86,838,904, reverse strand). Ensembl gene ENSG00000182050.
Subcellular location: Golgi apparatus membrane
Subcellular location (Human Protein Atlas): Plasma membrane; Vesicles; Centriolar satellite
Pathways (Reactome):
Disease: Maturation of spike protein
Metabolism of proteins: N-Glycan antennae elongation
Gene Ontology:
Molecular function: acetylglucosaminyltransferase activity; alpha-1,3-mannosylglycoprotein 4-beta-N-acetylglucosaminyltransferase activity
Biological process: protein N-linked glycosylation; viral protein processing
Cellular component: Golgi membrane
Genetic constraint (gnomAD): Loss-of-function variants: 15 observed, 35.62 expected, observed/expected ratio (o/e) 0.42, 90% interval 0.28 to 0.65. The upper end of that interval is the gene's LOEUF score, 0.65, which puts it in group 2 of 6, group 1 being the genes least tolerant of losing a copy. Missense variants: 448 observed, 539.34 expected, observed/expected ratio (o/e) 0.83, 90% interval 0.77 to 0.9. Synonymous variants: 165 observed, 182.2 expected, observed/expected ratio (o/e) 0.91, 90% interval 0.8 to 1.03.
Homologues: Orthologues: chimpanzee MGAT4C (100% identical), dog MGAT4C (96% identical), rat Mgat4c (96% identical), mouse Mgat4c (95% identical), rabbit MGAT4C (95% identical), macaque MGAT4C (93% identical), guinea pig MGAT4C (92% identical), pig MGAT4C (91% identical), zebrafish mgat4c (77% identical), tropical clawed frog mgat4c (75% identical), Drosophila melanogaster Mgat4a (29% identical), Drosophila melanogaster Mgat4b (22% identical). Paralogues in human: MGAT4A (30% identical), MGAT4B (30% identical), MGAT4D (18% identical).
Diseases named in the same sentence as MGAT4C in open-access papers:
MGAT4C is named in the same sentence as 9 diseases in open-access papers, as found by Europe PMC text mining. Sharing a sentence is not in itself a finding about the gene and the disease. The quoted sentences say what the papers report.
glioma (2 papers, 2022 to 2023). A benign or malignant brain and spinal cord tumor that arises from glial cells (astrocytes, oligodendrocytes, ependymal cells). "No published evidence was available as to the roles of the remaining eight underexpressed gene signatures (CHST9, CSDC2, ENHO, FERMT1, IGFN1, LINC00836, MGAT4C and SHANK2) regarding glioma pathogenesis or prognosis." (PMID 35456975, 2022).
pancreatic cancer (2 papers, 2020 to 2022). "Human GnT-IVc encoded by MGAT4C, also known as GnT-VI or GnT-IV-H, was cloned from the commonly deleted region in pancreatic cancer at 12q2146." (PMID 35854001, 2022). "Human GnT-IVc (MGAT4C), also known as GnT-VI and GnT-IV-H, was cloned from the commonly deleted region in pancreatic cancer at 12q21." (PMID 31936666, 2020).
prostate carcinoma (2 papers, 2021 to 2022). A carcinoma that arises from epithelial cells of the prostate gland. "MGAT4C overexpression in benign and cancer prostate cell lines significantly increases their proliferation and migration, and increasingly higher MGAT4C transcript levels are associated with prostate cancer progression." (PMID 35456975, 2022). "The results revealed that MGAT4C expression was related to the proliferation and migration of prostate cancer cells." (PMID 34366718, 2021).
depression (1 paper, 2025). "In fact, many of the depression-associated genes that underwent positive selection in both African and South Asian populations are immune-related, such as HLA-DQA1, HLA-DQB1, and MGAT4C." (PMID 40075226, 2025).
trypanosomiasis (1 paper, 2021). Infection with protozoa of the genus trypanosoma. "Additional genes highlighted in our study were CFH, TRNT1, IL5RA, MGAT4C and NTS, which could be also relevant for the trypanosomiasis resistance in cattle." (PMID 34351956, 2021).
cancer (4 papers, 2021 to 2023). A tumor composed of atypical neoplastic, often pleomorphic cells that invade other tissues. "MGAT4C, HSPA4L, ZSCAN5A, LOC100505841, and NALCN gene deletions were associated with cancer patients without FCH (p < 0.05), while SMYD3 and NKD2DSV genes were associated with cancer patients with FCH (p < 0.05)." (PMID 33431054, 2021).
MGAT4C also shares sentences with these, for which no sentence is quoted: autism (1 paper); cervical cancer (1); tumor (1).